HMGCS2 (3-hydroxy-3-methylglutaryl-CoA synthase 2)
Diseases named in the same sentence as HMGCS2 in open-access papers (continued):
Sharing a sentence is not in itself a finding about the gene and the disease.
cancer (42 papers, 2012 to 2025). A tumor composed of atypical neoplastic, often pleomorphic cells that invade other tissues. "Decreased TNF-α levels/Increased the relative abundance of Paracoides/Down-regulated three genes (Hmgcs2, Fabp2, and Gpt) associated with inflammation and cancer." (PMID 39712006, 2024). "The EPIC and quanTIseq databases further supported the association between HMGCS2 and immune cell infiltration in most cancer types." (PMID 37670031, 2023). "Results from the Timer database revealed that HMGCS2 expression was associated with immune cell infiltration in 25 cancers, with a particular focus on LIHC, TGCT, and BLCA." (PMID 37670031, 2023). "Our study elucidates a new molecular mechanism underlying the crosstalk between HMGCS2 expression and the KD in cancer treatment, which provides more information for precision medicine in developing personalized treatment strategies." (PMID 32635582, 2020). "Alternating the consumption of β‐glucan and quercetin significantly decreased the TNF‐α level, increased the relative abundance of Parabacteroides, and downregulated three genes (Hmgcs2, Fabp2, and Gpt) that are associated with inflammation and cancer." (PMID 31660141, 2019). "Here too cancer is associated with marked downregulation of HMGCS2 expression." (PMID 40305364, 2025). "Moreover, the altered intestinal ecosystem due to alternating the consumption of β‐glucan and quercetin can further result in the downregulation of 3 cancer‐associated genes (Hmgcs2, Fabp2, and Gpt)." (PMID 31660141, 2019). "Dsyregulation of genes involved in energy metabolism, such as Hmgcs2, have been observed in inflammatory conditions of the colon and during tumorigenesis, suggesting a potential link between enhanced colonic expression and reduced cancer risk." (PMID 22496968, 2012). "In the cellular lipid metabolism process, Bacteroides_sartorii was positively correlated with lipid metabolism-related gene of Mttp, cancer-related genes of Rbp2, and Dhrs9, but was also negatively correlated with cancer-related genes of Neu1 and Hmgcs2." (PMID 39727670, 2025). "Prominently, genes associated with primary liver metabolism, such as ARG1, UGT2R4, and HMGCS2, showed a downregulation rate of 81% in cancer lines." (PMID 39199347, 2024). "Further studies should be performed on the significance of HMGCS2 and statins in a drug‐tolerant cancer cell subpopulation." (PMID 38923428, 2024). "3-Hydroxy-3-methylglytaryl-CoA synthetase 2 (HMGCS2) controls the synthesis of ketone body β-hydroxybutyrate, but its activity is inhibited in cancers, resulting in the lower level of β-hydroxybutyrate produced by cancer cells." (PMID 37164974, 2023). "The transcription levels of HMGCS2 showed correlations with stromal scores in 13 cancers, immune scores in 11 cancers, and estimate scores in 12 cancers." (PMID 37670031, 2023). "In this study, HMGCS2 was found to be downregulated in almost all cancer tissues, suggesting its potential role as a suppressor." (PMID 37670031, 2023). "AKR1C1, CYP27A1, CYP2C9, GLB1, HMGCS2, and PLPP1, all six LMRGs, have been implicated in the genesis and progression of cancer." (PMID 36936948, 2023). "This study aims to systematically determine the expression patterns, prognostic value, and potential functions of HMGCS2 in different types of cancer." (PMID 37670031, 2023). "Subsequent survival analysis revealed correlations between HMGCS2 and clinical parameters in various cancers, particularly in LIHC and KIRC, which were further supported by Kaplan–Meier survival analysis." (PMID 37670031, 2023). "We observed significant correlations between HMGCS2 expression and stromal scores in 13 cancer types." (PMID 37670031, 2023). "In our pan-cancer analysis, the strong correlations of HMGCS2 with KIRC and LIHC prompted us to further validate its functions through cell biology experiments." (PMID 37670031, 2023).
cancer (continued). "Further, we identified mitochondrial 3-hydroxy-3-methylglutaryl-CoA synthase (HMGCS2) as a crucial regulator of cancer cell metabolism." (PMID 37692839, 2023). "To further investigate the role of HMGCS2 in energy metabolism in cancer cells, we measured oxidative phosphorylation and glycolysis using a Seahorse extracellular flux analyzer." (PMID 37692839, 2023). "To further investigate the correlation between HMGCS2 and immune cell infiltration across different cancer types, we conducted a comprehensive analysis using various databases." (PMID 37670031, 2023). "As expected, the mRNA levels of RPL22L1, INHBA, and CAPZA1 were significantly higher in cancer than in normal tissues; conversely, HMGCS2 was significantly downregulated in cancer." (PMID 35909892, 2022). "WGCNA revealed dMMR/MSI-correlated gene modules, including INHBA and RPL22L1, which were upregulated; conversely, HMGCS2 was downregulated in MSI cancer." (PMID 35909892, 2022). "INHBA, RPL22L1, CAPZA1, and HMGCS2 showed significant differential levels in dMMR/MSI cancer tissues and were finally selected for further detection." (PMID 35909892, 2022). "In HCC, the reduction of HMGCS2 is accompanied by a poor prognosis and promotes cancer cell migration." (PMID 33777129, 2021). "The Kaplan–Meier analysis also demonstrated that HMGCS2 down-regulation contributed to an unfavorable OS in liver and prostate cancer." (PMID 34830779, 2021). "Despite this low expression, however, we observed that - also in the stromal compartment - HMGCS2 and AKR1C3 were significantly higher in cancer-associated compared to benign areas." (PMID 31980029, 2020). "Recent studies have provided evidence that HMGCS2 showed altered expression levels and had prognostic implications in different human cancers." (PMID 31779269, 2019). "Expressed in liver and a number of extrahepatic tissues, like colon, HMGCS2 has also been reported to play a crucial preventive role in several cancers, such as rectal cancer, breast cancer, and prostate cancer." (PMID 31355161, 2019). "HMGCS2 can also increase the heterotopic expression of cancer cells to enhance the vitality of cancer cells." (PMID 31660141, 2019). "This analysis revealed striking differences in how the metabolism of a leukemic cell differs from that of a T cell and identified specific potential targets for cancer therapy, including Hmgcs2, Prodh, Ldhb, Fbp1, and Chdh." (PMID 30140438, 2018). "GeneGo pathway analysis revealed that cytoskeleton remodeling was at the top scale of the canonical pathway, further supporting the possibility of HMGCS2 controlling cancer cell motility." (PMID 27816970, 2017). "To study the roles of HMGCS2 in cancer progression, we first examined how its endogenous expression in wild-type CRC and OSCC cell lines correlates with cell motility." (PMID 27816970, 2017). "In vitro study showed that HMGCS2 enhanced cancer cell migration and invasion ability in an enzymatic-independent manner." (PMID 27816970, 2017). "In vitro, ectopic expression of HMGCS2 enhanced cancer cell motility in a ketogenesis-independent manner." (PMID 27816970, 2017). "Also, the activity of HMGCS2 was lower than that of the corresponding normal cell lines in poorly differentiated cancers, but elevated in higher-grade steroid-independent cancers." (PMID 39857793, 2025). "In this study, we investigated the role of HMGCS2 in pan-cancer through bioinformatic analysis." (PMID 37670031, 2023). "However, there have been limited systematic studies evaluating the role of HMGCS2 through pan-cancer analysis using bioinformatics approaches." (PMID 37670031, 2023). "Therefore, identifying the differential expression and roles of HMGCS2 across various tumors through pan-cancer analysis holds clinical significance." (PMID 37670031, 2023). "Additionally, significant correlations were observed between HMGCS2 expression and immune infiltration in 12 cancer types." (PMID 37670031, 2023).
cancer (continued). "Finally, in vitro experiments using cancer cell lines provided further evidence to support the role of HMGCS2 in cancer cell metabolism." (PMID 37692839, 2023). "HMGCS2 was downregulated in CRC cancer tissue and showed lower levels in MSI than in MSS." (PMID 35909892, 2022). "Interestingly, the expression and activity of HMGCS2 was shown to decrease in cancer cells, resulting in low BHB production." (PMID 36432618, 2022). "Regarding HMGCS2, it is confirmed by researchers as a cancer suppressor." (PMID 33777129, 2021). "The results demonstrated that the dysregulated genes in Huh-7 shHMGCS2 cells were enriched in pathways related to cancer progression, including TGF-β signaling pathway, tight junction, and pathways in cancer, which implied the possibility that HMGCS2 controls cancer cell motility and growth." (PMID 31779269, 2019). "Taken together, these results suggest that HMGCS2 may serve as a useful prognostic marker and vital target for future therapeutic strategies against advanced cancer." (PMID 27816970, 2017). "Growing evidence indicates that HMGCS2 may be involved in cancer progression, but its exact role is largely unknown." (PMID 27816970, 2017). "In summary, our study using clinical specimens, cellular experiments, and animal models suggest that HMGCS2 increases cancer cell invasion and metastasis ability via the HMGCS2/PPARα/Src signaling pathway, and plays in a ketogenesis enzymatic-independent manner." (PMID 27816970, 2017). "Our analysis revealed that mitochondrial 3-hydroxy-3-methylglutaryl-CoA synthase (HMGCS2), a key enzyme in ketogenesis and member of the HMG-CoA protein family, is a crucial regulator of cancer cell metabolism." (PMID 37692839, 2023). "Some of them have been reported as biomarkers in other types of cancers, such as GSTK1, IDH2, CAVIN3, HMGCS2, and ACOX1." (PMID 34557266, 2021). "Taken together, these results indicate that HMGCS2 physically interacted with PPARα, which was bound to the Src promoter, enhancing its transcriptional activity and subsequently increasing OSCC and CRC cell motility and cancer metastasis." (PMID 27816970, 2017). "The predicted estimation of being diagnosed with cancer from the log it model based on the five selected lipogenic genes panel, and Log it (P) = 0.429 + 0.659 x ACOT8 + 0.084 x ACSL5 + 0.029 x FASN + 0.201 x HMGCS2 + 0.119 x SCD1 was used to create the ROC curve." (PMID 32155177, 2020).
metabolic disorder (8 papers, 2020 to 2025). "Mutations in the HMGCS2 gene, which encodes this enzyme, lead to “mHS deficiency,” a rare, autosomal recessive, inherited metabolic disorder." (PMID 40943189, 2025). "Our findings contribute to a broader understanding of the clinical phenotype and expand the known spectrum of HMGCS2 gene variants, enhancing current knowledge of this rare metabolic disorder." (PMID 40004108, 2025). "Mitochondrial 3-hydroxy-3-methylglutaryl-CoA synthase deficiency (mitochondrial HMG-CoA synthase deficiency; HMGCS2D; OMIM#605911) is a rare autosomal recessive metabolic disorder caused by mutations in the HMGCS2 gene (OMIM*600234)." (PMID 35308163, 2021). "Loss-of-function mutations occur in HMGCS2 in humans, resulting in a severe metabolic disease." (PMID 40305364, 2025). "For example, Hmgcs2 and Bdh1, which are involved in ketogenesis, are upregulated by KD, suggesting a novel pathway for KD-ameliorated metabolic disorders." (PMID 38609395, 2024). "In humans, homozygous or compound heterozygous variants in HMGCS2 lead to HMGCS2 deficiency disorder (OMIM: 605911), a very rare, autosomal recessive metabolic disorder." (PMID 31910233, 2020).
inflammation (2 papers, 2022 to 2025). Aberrant reaction of the microcirculation characterized by movement of fluid and leukocytes from the blood into extravascular tissues. "Liver inflammation and fibrosis were not improved by HMGCS2-OE." (PMID 35421611, 2022).
cardiovascular diseases (1 paper, 2025). "Although primarily expressed in the liver under normal physiological conditions, the potential role of Hmgcs2 in cardiovascular diseases has been gradually revealed in recent years." (PMID 40159625, 2025).
heart (1 paper, 2025). "While heterogeneity is frequently considered a significant barrier in preclinical heart HFpEF research, we contest this view and posit that Hmgcs2 is upregulated in different HFpEF animal models utilising a combined transcriptomics and proteomics analysis." (PMID 40159625, 2025).
neurological disorders (1 paper, 2022). "HMGCS2 is involved in lipid-derived energy creation and fatty acid breakdown, with long-chain fatty acids offering neuron protection and are used as therapy against neurological disorders such as ASD." (PMID 35627199, 2022).
HMGCS2 also shares sentences with these, for which no sentence is quoted: Hepatic steatosis (6 papers); heart failure (4); Alzheimer disease (2); gastric cancer (2); inflammatory bowel disease (2); oral squamous cell carcinoma (2); aortic valve disease (1); cholangiocarcinoma (1); chronic hepatitis (1); chronic kidney disease (1); Cirrhosis (1); dermatitis (1); diabetic neuropathy (1); enteritis (1); erectile dysfunction (1); gonadal dysgenesis (1); Hypertension (1); hypertrophic cardiomyopathy (1); infection (1); kidney chromophobe (1); lentivirus infection (1); liver (1); maple syrup urine disease (1); MEHMO syndrome (1); metabolic acidosis (1); myocardial infarction (1); nephrolithiasis (1); nephropathy (1); ovarian carcinoma (1); rectosigmoid junction cancer (1).
A further 1 disease shares a sentence with HMGCS2 in 1 paper.